SOCS1 (suppressor of cytokine signaling 1)
Diseases named in the same sentence as SOCS1 in open-access papers (continued):
Sharing a sentence is not in itself a finding about the gene and the disease.
melanoma (continued). "SOCS1 silencing with short hairpin RNA affected tumor growth and the cell cycle, with arrest at the S phase and large-sized nuclei, reduced cell motility, and decreased melanoma cell invasion through Matrigel." (PMID 28079159, 2017). "In the present study, the expression of genes downregulated in SOCS1-silenced B16F10-Nex2 murine melanoma cells helped to characterize both the involvement of SOCS1 in the malignant context of murine melanoma and the intrinsic role of signaling pathways on the promotion of tumor progression." (PMID 28079159, 2017). "Presently, we show that Kit is poorly expressed in the SOCS1-silenced melanoma cell line." (PMID 28079159, 2017). "SOCS1 activates the transcription of genes involved in melanoma development." (PMID 28079159, 2017). "We therefore analyzed pSTAT3 levels in order to determine whether SOCS1 protein expression and basal STAT3 phosphorylation were associated in the panel of melanoma cell lines." (PMID 20398276, 2010). "However, SOCS1 has a dichotomous role in cancer development: It can also function as an oncogene, as evidenced by its overexpression at protein or mRNA levels in solid tumors like melanoma, directly correlating with heightened tumor invasion and growth." (PMID 38711523, 2024). "Silencing of SOCS1 by methylation is reported in hepatocellular carcinoma and other tumors like cervical cancer, hepatoblastoma, esophageal squamous cancers, melanoma, squamous cell carcinoma of the head and neck, pancreatic carcinoma and breast and ovarian cancer." (PMID 35421941, 2022). "In the near future, SOCS1 inhibition may also serve as an effective anti-melanoma immune effector." (PMID 30166456, 2018). "Moreover, high SOCS1 expression level correlates with the metastatic stage of the disease, suggesting that SOCS1 might be an additional marker of human melanoma progression." (PMID 26788993, 2016). "Melanoma-derived exosomes carrying miR-155 have also been shown to induce CAF differentiation and downregulate the expression of the suppressor of cytokine signaling 1 (SOCS1) gene in recipient fibroblasts." (PMID 39866233, 2025). "In a mouse model of melanoma, an in vivo CRISPR screen identified novel immunotherapy targets, including PTPN2 and SOCS1, both of which act to decrease IFN signaling." (PMID 31133614, 2019). "Results showed that SOCS1 downregulates TGF-β and BMP canonic pathways whereas activates MMP transcription factors through Smad independent activation, thus favoring EMT in melanoma cells." (PMID 28079159, 2017). "In contrast, overexpression of SOCS1, a negative regulator of IFN-y mediated signaling, has been previously observed in human melanoma." (PMID 24810760, 2014). "Depletion of SOCS1 negatively affects various tumor types like melanoma and neuroendocrine tumors supporting an oncogenic potential for the STAT1 inhibitor SOCS1." (PMID 24058673, 2013). "SOCS1 overexpression led to activation of STAT3 signaling and increase of MMP-2, and SOCS1−high melanoma cells enhanced invasive properties." (PMID 23231923, 2012). "Over-expression of SOCS1 and SOCS3 proteins in melanoma cells was achieved using the PINCO retroviral vector, while siRNA were used to inhibit SOCS1 and SOCS3 expression." (PMID 20398276, 2010). "The role for intratumoral SOCS1 and SOCS3 proteins as novel therapeutic targets remains deserves further evaluation in pre-clinical studies of melanoma or other malignancies." (PMID 20398276, 2010). "To further validate the role of SOCS protein expression in regulating IFN-responsiveness of representative human melanoma cell lines (HT144, 1259 MEL), we employed retroviral constructs that expressed SOCS1 and SOCS3." (PMID 20398276, 2010). "The present data suggest that SOCS1 and SOCS3 proteins represent a means by which melanoma cells can evade the direct effects of IFN-α and IFN-γ." (PMID 20398276, 2010). "SOCS1 and SOCS3 proteins were expressed at basal levels in melanocytes and in all melanoma cell lines examined." (PMID 20398276, 2010).
melanoma (continued). "Conversely siRNA-mediated inhibition of SOCS1 and SOCS3 expression enhanced the interferon-responsiveness of human melanoma cells." (PMID 20398276, 2010). "Immunoblot analysis revealed an induction of SOCS1 and SOCS3 proteins in some melanoma cell lines following a four hour stimulation with IFN-α (104 U/mL) or IFN-γ (10 ng/mL)." (PMID 20398276, 2010). "The present study demonstrates that SOCS1 and SOCS3 proteins were expressed in a panel of melanoma cell lines from various stages of disease and in melanocytes." (PMID 20398276, 2010). "Expression of SOCS1 and SOCS3 has been reported in melanoma cell lines and in surgical specimens obtained from malignant melanoma patients where it indicates a poor-prognosis." (PMID 20398276, 2010). "IFN-α and IFN-γ treatment led to further increases SOCS1 and SOCS3 expression in some human melanoma cell lines." (PMID 20398276, 2010). "Conversely, siRNA inhibition of SOCS1 and SOCS3 expression in melanoma cells enhanced their responsiveness to interferon stimulation." (PMID 20398276, 2010). "Over-expression of SOCS1 and SOCS3 proteins in melanoma cell lines led to a significant decrease in the IFN-responsiveness of melanoma cells." (PMID 20398276, 2010). "PEBP treatment reduced the expression of miR-210 and decreased expression levels of NF-κB-p65 via negative regulation of the SOCS1 gene, and, further, might reduce EMT invasion and migration in the metastasis of melanoma cells in vitro." (PMID 38255297, 2024). "Similarly to SOCS1, the role of SOCS3 in melanoma appears to be context-dependent, exhibiting both tumor-suppressive and pro-tumorigenic functions." (PMID 38975347, 2024). "SOCS1 also significantly diminished the metastatic capability of melanoma cells, as consequence of its negative control of STAT3 signaling and matrix metalloproteinase-2, basic fibroblast growth factor, and VEGF expression." (PMID 38975347, 2024). "Across 26 independent data sets and 15 donors, we consistently observed editing efficiencies of the SOCS1 gene of over 80% in KSQ-001, with editing of the SOCS1 gene resulting in complete depletion of SOCS1 protein in KSQ-001 manufactured from both NSCLC and melanoma donors." (PMID 38099496, 2023). "Transfection of human melanoma cell lines without or with very low levels of endogenous SOCS1 resulted in significantly decreased growth due to cell cycle arrest as well as increased apoptosis." (PMID 34639015, 2021). "In addition, exosomal miR-155 derived from melanoma cells upregulated the expression of proangiogenic factors, such as VEGF, FGF2, MMP9, in CAFs by targeting SOCS1/JAK2/STAT3 signaling pathway, which resulted in the increase of melanoma angiogenesis." (PMID 32489584, 2020). "The SOCS1-dependent expression of PD-L1 led us to examine the immunological response to SOCS1-silenced tumor cells and the cross-immune protection against B16F10-Nex2 melanoma cells." (PMID 28079159, 2017). "Conversely, SOCS1-silencing favors an anti-melanoma immune response by activation of effector T-CD8+ cells against the tumor, concomitant with regulation of ERK1/2 and p38 MAPK pathways and decreased expression of PD-L1 in murine melanoma B16F10-Nex2 cells." (PMID 28079159, 2017). "SOCS1-KIR exerted a negative effect on the enhanced tumorigenic potential of B16F1 melanoma cells by PSA." (PMID 28968979, 2017). "SOCS1-KIR exerted a negative effect on the enhanced the metastatic potential of B16F1 melanoma cells by PSA." (PMID 28968979, 2017). "For example, SOCS1, which is not expressed in normal skin or melanocytic nevi, is up-regulated in melanoma." (PMID 26788993, 2016). "Likewise, siRNA-mediated inhibition of SOCS1 and SOCS3 expression in melanoma cells enhances their responsiveness to IFN." (PMID 26788993, 2016). "We hypothesized that SOCS1 and SOCS3 proteins may down-regulate the biological response of melanoma cells to endogenous or exogenously administered interferons." (PMID 20398276, 2010).
melanoma (continued). "Basal and interferon-alpha (IFN-α) or interferon-gamma (IFN-γ)-induced expression of SOCS1 and SOCS3 proteins was evaluated by immunoblot analysis in a panel of n = 10 metastatic human melanoma cell lines, in human embryonic melanocytes (HEM), and radial or vertical growth phase melanoma cells." (PMID 20398276, 2010). "No increase in SOCS1 or SOCS3 expression was observed in any melanoma cell line transduced with the empty PINCO vector." (PMID 20398276, 2010). "SOCS1 protein expression was detected in ESTDAB-004 melanoma cells without treatment with IFN-γ and did not change after this treatment." (PMID 17319941, 2007). "To determine whether the overexpression of the SOCS proteins can directly affect melanoma invasion and/or suppress the effect of IFNβ, we prepared stable cell lines bearing EGFP-tagged doxycycline-inducible SOCS1 and SOCS3 (iSOCS1 and iSOCS3) gene expression constructs." (PMID 32872349, 2020). "Although the effect of SOCS1 or other SOCS family members (i.e. SOCS3) on IFN-α-responsiveness of melanoma cells was not evaluated in this prior study, our observations suggest that SOCS1 and SOCS3 could be a clinically relevant inhibitor of cytokine action." (PMID 20398276, 2010). "SOCS1 and SOCS3 expression and anti-tumor function have been also elucidated in skin cancer contexts, such as non-melanoma skin cancer (NMSC) and melanoma." (PMID 38975347, 2024).
hepatocellular carcinoma (51 papers, 2010 to 2024). A malignant tumor that arises from hepatocytes. "In this regard Ilangumaran and co-workers exhibited that hepatocellular carcinoma advances in SOCS1 deficiency through SOCS3-Dependent CDKN1A induction and NRF2 activation." (PMID 39286246, 2024). "SOCS1 deficiency, which increases susceptibility to hepatocellular carcinoma (HCC), promotes CDKN1A expression in the liver." (PMID 36765862, 2023). "For example, silencing of SOCS1 is associated with altered STAT3 activation in the development of hepatocellular carcinoma (HCC)." (PMID 33946612, 2021). "To understand the mechanisms of SOCS1-dependent regulation of elevated oxidative stress in hepatoma cells, we carried out a mass spectrometry analysis of the total proteome of the Hepa-vector and Hepa-SOCS1 cells after exposure to cisplatin or t-BHP for 3 h." (PMID 38254783, 2024). "The propensity of SOCS1-deficient mice to develop radiation-induced leukemias and their increased susceptibility to the experimental induction of colorectal cancer and hepatocellular carcinoma confirm that SOCS1 is a bona fide tumor suppressor." (PMID 38254783, 2024). "Genetic studies demonstrating the susceptibility of SOCS1-deficient mice to develop radiation-induced leukemias and to experimental induction of hepatocellular carcinoma and colorectal cancer confirm that SOCS1 is a bona fide tumor suppressor." (PMID 38415248, 2024). "Next, we compared the proteins modulated by SOCS1 in hepatoma cells after segregating them into downregulated or upregulated proteins." (PMID 38254783, 2024). "SOCS1 gene methylation has been well correlated with hepatocellular health as it is known to play a significant role in liver inflammation, hepatocellular cancer, and several other cancers, including colorectal cancer." (PMID 39414916, 2024). "MiR-155-5p modulates STAT1 expression suppressing SOCS1 expression in hepatoma cells and, thus, promoting the JAK/STAT signaling." (PMID 38098120, 2023). "Although SOCS1 has been found to have growth‐suppression activity in human hepatocellular carcinoma, it is also recognized as a tumor promoter in cancers due to different cellular contexts." (PMID 36127737, 2023). "Previous studies have also indicated that CpG island methylation in various carcinomas such as hepatocellular carcinoma, multiple myeloma, acute myeloid lymphoma, and colorectal cancer is responsible for silencing the SOCS-1 gene." (PMID 35733955, 2022). "Intriguingly, HCV permissive transformed hepatoma cell lines demonstrated higher intrinsic expression of SOCS1 and weaker ISGylation following IFN treatment." (PMID 36439639, 2022). "Downregulation of SOCS1 has been demonstrated in numerous malignancies such as prostate cancer, hepatocellular carcinoma, laryngeal carcinoma, multiple myeloma, acute myeloid leukemia, pancreatic cancer, and lymphoma." (PMID 30453988, 2018). "We also used data in TCGA from hepatocellular carcinoma, a tumor type where promoter DNA methylation often silences SOCS1 expression." (PMID 29081404, 2017). "SOCS-1 is silenced by methylation in human hepatocellular carcinoma and shows growth-suppression activity." (PMID 28915645, 2017). "In breast and hepatic carcinoma cells, expression levels of SOCS1 are down-regulated by the promoter DNA methylation, the reversal of which resulted in the induction of SOCS1 and anti-growth properties." (PMID 27613835, 2016). "For example, SOCS1 is frequently silenced by CpG island methylation in human hepatocellular carcinoma and frequently inactivated by hypermethylation in multiple myeloma." (PMID 25893382, 2015).
hepatocellular carcinoma (continued). "Nevertheless, previous studies have shown that SOCS1 CpG islands in human primary hepatocellular carcinomas (HCCs) are frequently methylated, suggesting that the epigenetic silencing of SOCS1 participates in tumor growth of HCCs." (PMID 20862390, 2010). "SOCS1 is a tumor suppressor in hepatocellular carcinoma (HCC)." (PMID 38254783, 2024). "SOCS1 has been found to be silenced in primary tumors in >50% of hepatocellular carcinoma, 44% of gastric carcinoma, 75% of melanoma, 40% of hepatoblastoma cases, 53–71% of pancreatic cancers and solid tumors, and in 60% of acute myeloid lymphoma and 62% of multiple myeloma." (PMID 37504269, 2023). "Inhibition of ANT2 may inhibit STAT3 activity by restoring SOCS1 expression and by downregulate miR-21, thereby exerting anticancer effects in human hepatocellular carcinoma cells." (PMID 34539732, 2021). "Methylation of SOCS-1 has been shown in 65% of hepatocellular carcinoma (HCC) cases." (PMID 34298667, 2021). "Furthermore, a high rate of methylation was detected on several SOCS genes, such as SOCS1 in hepatocellular carcinoma, SOCS3 in head and neck squamous cell carcinoma, and SOCS6 in GC." (PMID 33937336, 2021). "In the present study, miR-155 was over-expressed in human hepatoma cells (HepG2, H7402), and we found that SOCS1 expression was suppressed and subsequently the phosphorylation STAT1 and STAT3 were enhanced, which resulted in the induction of IFN-inducible genes expression." (PMID 21762537, 2011). "As SOCS1 is suppressed by miR-155, we speculated that miR-155 over-expression in human hepatoma cells may play a role in JAK/STAT signaling." (PMID 21762537, 2011). "Then we examined whether the translation level of SOCS1 was regulated by miR-155 in human hepatoma cells." (PMID 21762537, 2011). "HCV core protein induces SOCS3 expression in hepatoma cells, while it inhibits SOCS1 expression." (PMID 20862390, 2010). "Different alterations of SOCS1 expression contribute to this mechanism, beginning with SOCS1 silencing through hypermethylation of its promoter region, observed in diverse malignant diseases such as pancreatic carcinoma, acute myeloid leukemia, and hepatocellular carcinoma (HCC)." (PMID 38711523, 2024). "The Suppressor of cytokine signaling 1 (SOCS1) gene is frequently repressed by CpG methylation in up to 65% of primary hepatocellular carcinoma (HCC), suggesting that SOCS1 functions as a tumor suppressor in hepatocytes." (PMID 36765862, 2023). "This study investigated the role of HCV infection on SOCS-1 in normal and HCV-infected tissues and revealed a possible mechanism underlying HCV-induced hepatocellular carcinoma (HCC) genesis." (PMID 35733955, 2022). "Here, we investigated the clinical relevance of SOCS1 methylation and modulation upon epigenetic therapy in diverse cellular populations of hepatocellular carcinoma (HCC)." (PMID 34679523, 2021). "SOCS1, which was identified as a tumor suppressor gene for hepatocellular carcinoma (HCC), was found to be upregulated in hepatocytes and was associated with a good prognosis." (PMID 34616431, 2021). "The suppressor of cytokine signaling 1 (SOCS1) protein is considered a tumor suppressor because of frequent repression of the SOCS1 gene promoter by CpG methylation in many types of cancers including hepatocellular carcinoma, leukemia and pancreatic adenocarcinoma." (PMID 28235401, 2017). "Deletion or silencing of SOCS1 in human hepatocellular carcinoma (HCC), acute myeloid leukemia and gastric cancer also points to the anti-tumor potential of SOCS1." (PMID 24058673, 2013). "The SOCS1-mediated attenuation of NRF2 and p21 protein expression also occurred in human Hep3B hepatoma cells expressing SOCS1 (Hep3B-SOCS1) exposed to t-BHP." (PMID 38254783, 2024).
hepatocellular carcinoma (continued). "Since low SOCS1 gene expression correlates with poor prognosis in the TCGA-liver hepatocellular carcinoma (LIHC) dataset, and high GCLC in HCC tissues correlates with poor prognosis, we evaluated the relationship between SOCS1, NFE2L2 (NRF2) and GCLC gene expression in the TCGA-LIHC dataset." (PMID 38254783, 2024). "MiR-155 enhances innate antiviral immunity through promoting JAK/STAT signaling pathway by targeting SOCS1, and mildly inhibits HBV infection in human hepatoma cells." (PMID 21762537, 2011). "miR-155, as a positive regulator of JAK/STAT signaling by targeting SOCS1, increases the expression of IFN-inducible antiviral genes and enhances innate antiviral immunity in human hepatoma cells." (PMID 21762537, 2011). "After treatment with diethylnitrosamin (DEN), a chemical agent that induces hepatocellular carcinoma (HCC), SOCS1 heterozygous mice developed more tumors than wild type mice." (PMID 20862390, 2010). "Whereas the tumor suppressor role of SOCS1 has been genetically confirmed in mouse models of colorectal cancer and hepatocellular carcinoma, the mechanisms of SOCS1-mediated tumor suppression are not yet completely understood." (PMID 38254783, 2024). "Here we show that SOCS1 was differentially expressed at higher levels in HNSCC and served as a significant and independent prognostic factor for HNSCC, consistent with its role in hepatocellular carcinoma." (PMID 34527677, 2021). "We establish, based on quantitative measurements obtained for the hepatoma cell line Huh7.5, an ordinary differential equation model for IFNα signal transduction that comprises the feedback regulators STAT1, STAT2, IRF9, USP18, SOCS1, SOCS3, and IRF2." (PMID 32696599, 2020). "The reverse correlation found between hypermethylation and silenced SOCS-3 was tested in the second exon (gene body), not in the promoter region, and hypermethylation of SOCS-1 promoter was found in certain hepatocellular carcinoma cell lines." (PMID 30987235, 2019). "miR-155 was reported to promote invasiveness of pancreatic cancer cells, through regulating suppressor of cytokine signaling 1 (SOCS1) and P-signal transducer and activator of transcription-3 (STAT3), and promote the hepatocellular carcinoma progression by targeting PTEN." (PMID 30046565, 2018). "SOCS1 and SOCS3 genes are considered tumor suppressors in hepatocellular carcinoma (HCC) due to frequent epigenetic repression." (PMID 32807134, 2020). "Aberrant methylation of SOCS1 silences SOCS1 and activates the JAK2/STAT3 pathway in hepatocellular carcinoma cells (HCC), resulting in the development of HCC." (PMID 30285793, 2018).